SLCO2B1 (solute carrier organic anion transporter family member 2B1)
Description:
Mediates the Na(+)-independent transport of steroid sulfate conjugates and other specific organic anions. Responsible for the transport of estrone 3-sulfate (E1S) through the basal membrane of syncytiotrophoblast, highlighting a potential role in the placental absorption of fetal-derived sulfated steroids including the steroid hormone precursor dehydroepiandrosterone sulfate (DHEA-S). Also facilitates the uptake of sulfated steroids at the basal/sinusoidal membrane of hepatocytes, therefore accounting for the major part of organic anions clearance of liver. Mediates the intestinal uptake of sulfated steroids. Mediates the uptake of the neurosteroids DHEA-S and pregnenolone sulfate (PregS) into the endothelial cells of the blood-brain barrier as the first step to enter the brain. Also plays a role in the reuptake of neuropeptides such as substance P/TAC1 and vasoactive intestinal peptide/VIP released from retinal neurons. May act as a heme transporter that promotes cellular iron availability via heme oxygenase/HMOX2 and independently of TFRC. Also transports heme by-product coproporphyrin III (CPIII), and may be involved in their hepatic disposition. Mediates the uptake of other substrates such as prostaglandins D2 (PGD2), E1 (PGE1) and E2 (PGE2), taurocholate, L-thyroxine, leukotriene C4 and thromboxane B2 (PubMed:10873595, PubMed:14610227, PubMed:19129463, PubMed:29871943, Ref.25). May contribute to regulate the transport of organic compounds in testis across the blood-testis-barrier (Probable). Shows a pH-sensitive substrate specificity which may be ascribed to the protonation state of the binding site and leads to a stimulation of substrate transport in an acidic microenvironment. The exact transport mechanism has not been yet deciphered but most likely involves an anion exchange, coupling the cellular uptake of organic substrate with the efflux of an anionic compound. Hydrogencarbonate/HCO3(-) acts as a probable counteranion that exchanges for organic anions. Cytoplasmic glutamate may also act as counteranion in the placenta. An inwardly directed proton gradient has also been proposed as the driving force of E1S uptake with a (H(+):E1S) stoichiometry of (1:1). [Isoform 3]: Has estrone 3-sulfate (E1S) transport activity comparable with the full-length isoform 1.
Synonyms: OATP-B; OATP2B1; OATPB; SLC21A9
Tractability: Small molecule: it belongs to a druggable protein family. Antibody: UniProt places it where antibodies can reach, with high confidence; its Gene Ontology location is reachable by antibodies, with high confidence; UniProt predicts a signal peptide or a membrane-spanning region. PROTAC: its protein half-life has been measured; a small molecule that binds it is known.
Target class: Electrochemical transporter; SLC superfamily of solute carriers; SLC21/SLCO family of organic anion transporting polypeptides; Transporter
Gene: Protein-coding gene on chromosome 11 (75,100,563 to 75,206,549, forward strand). Ensembl gene ENSG00000137491.
Subcellular location: Cell membrane; Basal cell membrane; Basolateral cell membrane; Apical cell membrane
Pathways (Reactome):
Drug ADME: Aspirin ADME; Atorvastatin ADME
Metabolism: Heme degradation
Transport of small molecules: Organic anion transport by SLCO transporters
Gene Ontology:
Molecular function: prostaglandin transmembrane transporter activity; protein binding; secondary active transmembrane transporter activity; transmembrane transporter activity
Biological process: transmembrane transport; heme catabolic process; sodium-independent organic anion transport; transport across blood-brain barrier; xenobiotic metabolic process; prostaglandin transport
Cellular component: apical plasma membrane; basal plasma membrane; basolateral plasma membrane; plasma membrane; membrane
Genetic constraint (gnomAD): Loss-of-function variants: 39 observed, 66.01 expected, observed/expected ratio (o/e) 0.59, 90% interval 0.46 to 0.77. The upper end of that interval is the gene's LOEUF score, 0.77, which puts it in group 3 of 6, group 1 being the genes least tolerant of losing a copy. Missense variants: 820 observed, 934.69 expected, observed/expected ratio (o/e) 0.88, 90% interval 0.83 to 0.93. Synonymous variants: 377 observed, 386.87 expected, observed/expected ratio (o/e) 0.97, 90% interval 0.89 to 1.06.
Homologues: Orthologues: chimpanzee SLCO2B1 (99% identical), macaque SLCO2B1 (97% identical), pig SLCO2B1 (81% identical), dog SLCO2B1 (79% identical), rabbit SLCO2B1 (79% identical), guinea pig SLCO2B1 (77% identical), rat Slco2b1 (74% identical), mouse Slco2b1 (73% identical), tropical clawed frog slco2b1 (47% identical), zebrafish slco2b1 (42% identical), Drosophila melanogaster Oatp30B (27% identical). Paralogues in human: SLCO2A1 (38% identical), SLCO5A1 (29% identical), SLCO1B3 (29% identical), SLCO3A1 (29% identical), SLCO1B1 (29% identical), SLCO1C1 (28% identical), SLCO1A2 (27% identical), SLCO4A1 (26% identical), SLCO4C1 (26% identical), SLCO6A1 (19% identical).